ERBB2 (erb-b2 receptor tyrosine kinase 2)
Diseases named in the same sentence as ERBB2 in open-access papers (continued):
Sharing a sentence is not in itself a finding about the gene and the disease.
asthma (15 papers, 2016 to 2025). "A functional exonic variant of ERBB2 has been shown to play a role in asthma development by modulating the MAPK signaling cascade." (PMID 39769348, 2024). "The > 290 kb distance between the promoter of ERBB2 and its eSNPs (rs2270401, rs2302774) suggested a long-range interaction between ERBB2 and the region harboring both cg10374813 and the asthma-associated SNPs (rs2270401, rs2302774)." (PMID 34629083, 2021). "In accordance with the current study, ERBB2 was found to be strongly associated with severe-to-moderate and severe asthma." (PMID 32512817, 2020). "The most significant association signal was driven by the SNP rs2952156 located at the Erb-B2 Receptor Tyrosine Kinase 2 (ERBB2) gene, whose G allele was associated with protection for asthma (OR = 0.87, p = 2.20 × 10−30) in ethnically diverse populations." (PMID 30805318, 2019). "In addition, DDX5 is known to be a hub gene of the cilia module in asthma and a regulator of ERBB2, which is associated with epithelial repair processes in asthma patients." (PMID 37875944, 2023). "The remaining two eQTL-meQTL-GWAS triplets spanned the entire locus, included two eQTLs for ERBB2, which is located at the proximal end of the locus, more than 290 kb from the two colocalized asthma risk variants rs2270401 (childhood onset) and rs2302774 (TAGC) at the distal end of the locus." (PMID 34629083, 2021). "The SNPs that were eQTLs for ERBB2 in RV infected epithelial cells showed strong evidence of association with asthma (childhood onset asthma pGWAS = 8.11 × 10−29; TAGC pGWAS = 2.79 × 10−20), directly connecting the eQTL for ERBB2 in RV-treated cells to asthma risk." (PMID 34629083, 2021). "Immune infiltration analysis further supported the relevance of these targets, linking HSP90AB1 and ERBB2 expression to M2 macrophage polarization and highlighting asthma-specific immune dysregulation." (PMID 41403444, 2025). "Despite these limitations, our study identifies seven core targets (HSP90AB1, CCNB1, CCK, CDK6, CASP9, NR3C1, and ERBB2) that offer promising avenues for developing novel asthma therapies." (PMID 41403444, 2025). "SNPs extending both proximal (including PGAP3 and ERBB2) and distal (including GSDMA) to the core region show less LD with those in the core region and have been implicated as potentially independent asthma risk loci." (PMID 34629083, 2021). "The asthma risk alleles in the childhood onset asthma (rs2270401-A) and TAGC (rs2302774-G) GWASs were associated with hypermethylation of cg10374813 in both conditions and decreased ERBB2 expression only in RV-treated cells." (PMID 34629083, 2021). "In relation to asthma pathogenesis, several reports described the results that ErbB2 expression is impaired in asthmatic airway epithelium." (PMID 33217964, 2020). "The CD1C, TLR7, PTK2, CD1E, CD1A, and ERBB2 genes had a higher rate of engaging protein interactions in the PPI for the moderate-to-severe asthma phenotype." (PMID 32512817, 2020). "Erb-B2 tyrosine kinase 2 (ErbB2) was found to be highly correlated with asthma and was suggested to be a novel therapeutic target for asthma." (PMID 32512817, 2020). "ERBB2 mediates epithelial repair processes, and this function may be defective in subjects with asthma and co-opted by type 2 inflammatory processes." (PMID 32887352, 2020). "In pathways downregulated in asthma cases, hub genes were identified reflecting the importance of impaired wound healing: FN1 and ERBB2 35,36." (PMID 38806494, 2024). "They concluded that certain SNP occurrences in genes such as CD247, ERBB2, IL1RL1 and several interleukin family genes are strongly correlated with moderate-to-severe asthma." (PMID 32512817, 2020). "The combined interaction scores resulted in higher interactions for the genes STAT3, AGO2, COL1A1, CLCN6, and KSR for moderate asthma and JAK2, INSR, ERBB2, NR3C1, and PTK6 for severe asthma." (PMID 32512817, 2020).
asthma (continued). "Critically, NR3C1, HSP90AB1, and ERBB2 collectively suppress plasma cells (unified negative correlations), implicating synergistic control of humoral immunity dysregulation in asthma." (PMID 41403444, 2025). "Our findings support a role for enhanced EGFR signalling in asthma airway remodelling and might suggest a functional involvement of ERBB2, also known as human epidermal growth factor receptor 2 (HER2), and ERBB4, also known as HER4, in its pathogenesis." (PMID 39401856, 2024). "Moreover, genes related to growth and development (e.g., ERBB2, CDK2, PGAP3) were upregulated in asthma, which led to the feature of airway remodeling in the asthmatic monkeys." (PMID 36439114, 2022). "For example, in severe asthma, the combined interaction scores for the STAT3, AGO2, COL1A1, CLCN6, and KSR1 genes yielded a higher interaction for the moderate asthma phenotype, and the JAK2, INSR, ERBB2, NR3C1, and PTK6 genes were more interactive for the severe asthma phenotype." (PMID 32512817, 2020). "To date, the function of ERBB2 in asthma has not been investigated." (PMID 29367592, 2018).
chordoma (15 papers, 2011 to 2025). Chordomas are rare malignant tumors arising from embryonic remnants of the notochord in axial skeleton. "Other potential target classes for the combination with CDK inhibitors could be EGFR/ERBB2 inhibitors or p300 inhibitors, which have previously been reported as having antiproliferative effects on chordomas." (PMID 38786326, 2024). "Chordomas express stem cell factor receptor (c-KIT), platelet-derived growth factor receptors (PDGFR-α and PDGFR-β), receptor tyrosine-protein kinase erbB-2 (HER2/neu), and epidermal growth factor receptor (EGFR)." (PMID 27659533, 2016). "Furthermore, EGFR activation has also been reported, and an European multi-center trial is evaluating the efficacy of afatinib, an ERBB family (EGFR/ERBB1, HER2/ERBB2, ERBB3, and ERBB4) inhibitor, as first-line or later-line treatment in advanced chordoma (NCT03083678)." (PMID 34868903, 2021).
COVID-19 (15 papers, 2020 to 2025). A disease caused by infection with severe acute respiratory syndrome coronavirus 2. "By contrast, in vivo studies to explore COVID-19 and cancer recurrence would likely be challenging, as they should employ mice with multiple genetic modifications predisposing to both COVID-19 and cancer (such as mice transgenic for hACE2 and ErbB2/Neu)." (PMID 33194755, 2020). "Further bioinformatic analysis revealed 8 core targets (EGFR, AR, ESR1, MAPK8, MDM2, EZH2, ERBB2 and MAPT) in the VitD-COVID-19-osteoporosis network." (PMID 36307516, 2022). "The analysis of COVID-19 extended interactome indicates several membrane bound gene/proteins (i.e., ICAM1, EGFR, ERBB2, APP, ADR2, FAS, CDH1, and MAPT), whose activity and/or expression could be affected by SARS-CoV-2 challenge." (PMID 33123533, 2020). "With regard to interaction with ERBB2, a key molecule in estrogen signaling involved in the upstream molecular network of MACROH2A1; ERBB2 was reported to interact with MACROH2A1.2, but not with MACROH2A1.1, which might result in MACROH2A1.2-specific function in severe COVID-19 pathogenesis." (PMID 36451245, 2022).
oral squamous cell carcinoma (15 papers, 2004 to 2025). "The overexpression of HER-2 (neu/erbB2) is correlated with a poor prognosis in patients with breast cancer or oral squamous cell carcinoma, presumably due to an increased metastatic ability and resistance to various cancer chemotherapies." (PMID 22084729, 2011).
signet ring cell carcinoma (15 papers, 2008 to 2026). A usually aggressive, poorly differentiated invasive adenocarcinoma characterized by the presence of malignant glandular cells in which the nucleus is pressed to one side by the presence of intracytoplasmic mucus. "In many of the signet ring cell carcinoma cell lines, the ErbB2/ErbB3 pathway is often constitutively activated by the autocrine loop of ErbB2-ErbB3-Muc4-ErbB2." (PMID 22216327, 2011). "It appears that there are two types of signet ring carcinomas: ErbB2/ERbB3 activated and non-activated." (PMID 22216327, 2011).
meningioma (14 papers, 2010 to 2025). A generally slow growing tumor attached to the dura mater. "Additionally, underexpression of ERBB2 is significantly associated with meningioma recurrence following surgical resection." (PMID 27007654, 2016). "In Watson’s dataset, the expression of ERBB2 was 5.166 times higher in meningioma tissues than in normal tissues." (PMID 33892666, 2021). "ErbB2/HER2 is generally upregulated in human meningiomas, but in an activated state only in a few cases." (PMID 30335819, 2018). "ERBB2 expression was positive in 88.3% of the meningiomas studied, with 31.7% weak, 38.3% moderate, and 18.3% strong." (PMID 27007654, 2016). "The present study found that 88.3% of meningiomas were ERBB2-positive; 31.7% had weak, 38.3% had moderate, and 18.3% had strong ERBB2 expression levels." (PMID 27007654, 2016). "Mahzouni and Movahedipour evaluated 72 meningiomas and reported that 43% were ERBB2-positive with 55% grade I and 38.5% grades II and III." (PMID 27007654, 2016). "DEG analysis identified 250 and 68 significantly overexpressed genes in the VS and meningioma tumour samples respectively compared to their control tissues, including six significantly co-overexpressed genes: COL1A, ERBB2, SLFN12, SLIT2, PDGFD and CDH1." (PMID 41437121, 2025). "ErbB2/HER2 status is important in the medical management of patients with various human malignancies, whereas its clinical relevance in human meningiomas is ambiguous." (PMID 30335819, 2018). "We have investigated the expression of merlin, NDRG2, ERBB2, and c-MYC in patient meningioma specimens using immunohistochemistry (IHC)." (PMID 27007654, 2016). "We determined expression of the proteins merlin, NDRG2, ERBB2, and c-MYC in meningiomas using immunohistochemistry and assessed relationships between protein expression and gender, age, tumor grade, and recurrence or regrowth." (PMID 27007654, 2016). "Expression of merlin, NDRG2, ERBB2, and c-MYC was not significantly different statistically with relation to gender, age, or meningioma recurrence or regrowth." (PMID 27007654, 2016). "Additionally, there were eight kinases that were not significantly differently expressed between meningioma and VS present in the macrophages (LCK, PDGFRB, FGFR1, FLT1, CSK, MEK, MAP2K2, and ERBB2)." (PMID 41437121, 2025).
respiratory failure (14 papers, 2013 to 2025). The significant impairment of gas exchange within the lungs resulting in hypoxia, hypercarbia, or both, to the extent that organ tissue perfusion is severely compromised. "Animals carrying a hypomorphic Erbb2 allele expressing 10% of wild-type protein levels in trans to a null allele demonstrated perinatal lethality due to impaired diaphragm innervation causing respiratory failure." (PMID 25269082, 2014). "However, the authors reported massive T-cell activation and clinical respiratory failure triggered by the physiological levels of ERBB2 expressed on normal lung epithelium." (PMID 28885562, 2017). "In addition, a dramatic case was reported, in which a patient with metastatic colon carcinoma was treated with anti-ERBB2-CAR-Ts and subsequently died of respiratory failure, which was attributed to “on-target/off-tumor” toxicities in the lung." (PMID 37915564, 2023).
brain cancer (13 papers, 2009 to 2025). A primary or metastatic malignant neoplasm affecting the brain. "Some of the uniquely expressed genes include CD44 (quantified in FPW1), ERBB2 (quantified in RN1), and OLIG2 (quantified in PB1) and are genes with key roles in brain cancer." (PMID 31973233, 2020).
cervical adenocarcinoma (13 papers, 2004 to 2025). An adenocarcinoma arising from the cervical epithelium. "The first involved a 63-year-old female patient with cervical adenocarcinoma and ErbB2 overexpression identified by IHC, who achieved a best RECIST response of PR (−65%) by the end of cycle 6 and maintained this PR for >14 months." (PMID 39908697, 2025). "In a prior retrospective study, we identified mutations in FAT1, ARID1A, ERBB2, and PIK3CA in whole-exome sequencing of 15 patients with cervical adenocarcinoma." (PMID 34203201, 2021). "Similarly, in cervical adenocarcinomas, the integration of HPV DNA into hotspots such as STARD3 and ERBB2 was correlated with increased protein expression pf STARD3 and ERBB2, respectively." (PMID 39858090, 2025). "ERBB2 (HER2) mutations and PD-L1 expression are considered to be promising prognostic markers in cervical adenocarcinomas, but at present this question is not completely clear." (PMID 34830452, 2021).
endometrial tumors (13 papers, 2003 to 2025). "Further, addressing intratumoral heterogeneity in endometrial tumors is crucial, particularly whether amplicon-based NGS assays can detect ERBB2 amplification if only a small portion of the tumor is amplified, even with overall tumor cellularity greater than 30%." (PMID 39682116, 2024).
metastatic prostate carcinoma (13 papers, 2012 to 2026). A carcinoma that arises from the prostate gland and has spread to other anatomic sites. "Aberrant activation of the erb-b2 receptor tyrosine kinase 2 (ERBB2) has been found to play a critical role in metastatic prostate cancer." (PMID 28422721, 2017). "Cell signaling pathways activated by the ERBB2 oncogene or the RAS oncogene are frequently found to be altered in metastatic prostate cancers." (PMID 24937171, 2014).
mucinous tumors (13 papers, 2011 to 2024). "Among mucinous tumors, the most prevalent mutations occur in the mitogen activated protein kinase (MAPK) pathway, including KRAS mutations and ERBB2 amplification/overexpression." (PMID 25986173, 2015). "ERBB2, a gene implicated in breast and EOC showed significant focal amplification in mucinous tumors but deletions in serous tumors." (PMID 23078675, 2012). "In our ovarian cases, one mucinous tumor, MUC1, harbours a fusion between ERBB2 and adjacent PERLD1 caused by an underlying genomic inversion." (PMID 21625565, 2011). "ERBB2 is significantly amplified in mucinous tumors and is a candidate copy number driver gene." (PMID 23078675, 2012). "These include: FH, GMPS, PIK3CA, EIF4A2, ZNF384, and SS18L1 (amplifications in serous tumors); TET2, FGFR10P, NF1, ERBB2, and SH3GL1 (deletions in serous tumors) and ERBB2 (amplifications in mucinous tumors)." (PMID 23078675, 2012).
pulmonary fibrosis (13 papers, 2010 to 2025). Chronic progressive interstitial lung disorder characterized by the replacement of the lung tissue by connective tissue, leading to progressive dyspnea, respiratory failure, or right heart failure. "Of these six master regulators, three master regulators are found to be associated with pulmonary fibrosis (ERBB2, EGFR and FGFR2) and one with inflammation (FYN)." (PMID 37206915, 2023). "Next, we explored the cell types in which RDN improved the progression of pulmonary fibrosis by downregulating the activation of ERBB2." (PMID 36605402, 2022). "This study innovatively proposed that Reduning could prevent sepsis-induced pulmonary fibrosis through ERBB2 as a target." (PMID 36605402, 2022). "In conclusion, downregulating the ERBB2-p38 MAPK signaling pathway in AMs may prevent sepsis-induced pulmonary fibrosis, pointing to a potential therapeutic target." (PMID 36605402, 2022). "Discussion: Reduning may prevent sepsis-induced pulmonary fibrosis by regulating the ERBB2-p38 MAPK signaling pathway, which provides a possibility for the prevention of sepsis-induced pulmonary fibrosis with traditional Chinese medicine." (PMID 36605402, 2022). "Therefore, the results partly elucidated that Reduning may attenuate sepsis-induced pulmonary fibrosis by regulating the ERBB2/HER2-p38 MAPK signaling pathway in AMs." (PMID 36605402, 2022). "Since both cancer and fibrosis have been reported to be closely associated with chronic inflammation, we hypothesized that the active components stigmasterol, quercetin, and beta-sitosterol of Reduning may inhibit p-ERBB2/HER2-MAPK to block the progression of sepsis-induced pulmonary fibrosis." (PMID 36605402, 2022). "Network pharmacology and molecular docking results showed Reduning may regulate ERBB2 phosphorylation and the MAPK signaling pathway through stigmasterol, quercetin, and beta-sitosterol, thereby preventing sepsis-induced pulmonary fibrosis." (PMID 36605402, 2022). "Molecular validation experiments confirmed RDN could alleviate lung fibrosis induced by cecum ligation and puncture (CLP), in parallel with the inhibition of the ERBB2-p38 MAPK pathway in mouse alveolar macrophages (AMs)." (PMID 36605402, 2022). "Some anticancer therapies, such as those targeting erbB2 (an EGF receptor family member) with monoclonal antibodies, might be considered for lung fibrosis therapy to reduce mesenchymal cell survival and resolve a fibrotic reaction." (PMID 20738867, 2010).
Alzheimer disease (12 papers, 2013 to 2025). A progressive, neurodegenerative disease characterized by loss of function and death of nerve cells in several areas of the brain leading to loss of cognitive function such as memory and language. "The genes associated with Alzheimer’s disease were Erb-B2 receptor tyrosine kinase 2 (ERBB2), Cystatin B (CSTB), and Caspase 6 (CASP6)." (PMID 34379632, 2021). "ERBB2 has previously been shown to decrease expression in the hippocampus of normal adult mice and humans with increased expression in the hippocampus linked to Alzheimer’s disease." (PMID 34379632, 2021). "Furthermore, downregulation of ErbB-2 and ErbB-3 genes is associated with neuro-degenerative diseases such as multiple sclerosis and Alzheimer's disease." (PMID 26559525, 2015). "Tyrphostin AG 825 is a selective, ATP-competitive ErbB2 inhibitor that inhibits tyrosine phosphorylation, as a potential anti-Alzheimer’s disease drug, it has been confirmed to have effects on anticancer, accelerating neutrophil apoptosis." (PMID 38846957, 2024). "Our study demonstrates an increase of ERBB2 expression in the PFC in normal aging, supporting further study into the role that this gene may be playing in the PFC as a risk factor in Alzheimer’s disease." (PMID 34379632, 2021). "Signaling by ERBB2 and KRAS play important roles in the development and progression of Alzheimer’s Disease." (PMID 36227739, 2022).